CD302 (CD302 molecule)
Description:
Multifunctional C-type lectin receptor involved in endocytosis, phagocytosis and regulation of cell adhesion and migration. Plays a critical role in guiding dendritic cells to lymph nodes. Also functions as a restriction factor for Hepatitis C virus (HCV) at the liver cell surface, likely by inhibiting a viral cell entry step.
Synonyms: CLEC13A; DCL1; KIAA0022; DCL-1; BIMLEC
Tractability: Antibody: UniProt predicts a signal peptide or a membrane-spanning region. PROTAC: its protein half-life has been measured.
Gene: Protein-coding gene on chromosome 2 (159,768,628 to 159,798,255, reverse strand). Ensembl gene ENSG00000241399.
Subcellular location: Cell membrane; Cell projection, filopodium; Cytoplasm, cell cortex; Cell projection, microvillus
Gene Ontology:
Molecular function: protein binding
Biological process: phagocytosis
Cellular component: cell cortex; filopodium; membrane; plasma membrane; microvillus
Genetic constraint (gnomAD): Loss-of-function variants: 18 observed, 20.96 expected, observed/expected ratio (o/e) 0.86, 90% interval 0.59 to 1.27. The upper end of that interval is the gene's LOEUF score, 1.27, which puts it in group 5 of 6, group 1 being the genes least tolerant of losing a copy. Missense variants: 264 observed, 254.63 expected, observed/expected ratio (o/e) 1.04, 90% interval 0.94 to 1.15. Synonymous variants: 86 observed, 92.13 expected, observed/expected ratio (o/e) 0.93, 90% interval 0.78 to 1.12.
Homologues: Orthologues: chimpanzee CD302 (99% identical), macaque CD302 (94% identical), pig CD302 (83% identical), guinea pig CD302 (82% identical), rabbit CD302 (78% identical), dog CD302 (78% identical), mouse Cd302 (74% identical), rat Cd302 (59% identical), tropical clawed frog CD302 (37% identical), zebrafish cd302 (30% identical), Caenorhabditis elegans clec-161 (9% identical). Paralogues in human: MRC1 (23% identical), MRC2 (21% identical), LY75 (19% identical), PLA2R1 (16% identical).
Diseases named in the same sentence as CD302 in open-access papers:
CD302 is named in the same sentence as 38 diseases in open-access papers, as found by Europe PMC text mining. Sharing a sentence is not in itself a finding about the gene and the disease. The quoted sentences say what the papers report.
acute myeloid leukemia (3 papers, 2019 to 2025). Acute myeloid leukemia (AML) is a group of neoplasms arising from precursor cells committed to the myeloid cell-line differentiation. "As C-type lectin receptor, CD302 has roles in cell immune and migration, and acts as a prognostic biomarker in myeloma, is also a potential therapeutic target for acute myeloid leukemia." (PMID 32775301, 2020). "In primary acute myeloid leukemia (AML), CD302 is primarily expressed in leukemia stem cells (LSCs) and progenitor cells, with its expression being relatively limited in normal hematopoietic cells." (PMID 41323386, 2025). "In acute myeloid leukemia (AML), CD302 is highly expressed in bone marrow immune populations and correlates positively with CD33, a clinical AML biomarker." (PMID 41323386, 2025).
lung carcinoma (3 papers, 2014 to 2025). "CLEC3B and CD302 have been verified downregulated in lung cancer and having the diagnostic and prognostic values in lung cancer." (PMID 37325647, 2023). "However, CD302’s role in other lung cancer subtypes, particularly lung adenocarcinoma (LUAD), remains underexplored." (PMID 41323386, 2025). "Given the differences in pathogenesis and clinicopathological features among various lung cancer subtypes, investigating the role of CD302 in LUAD may hold significant research and clinical value." (PMID 41323386, 2025). "However, research on CD302 in other lung cancer subtypes remains limited, and to date, no studies have reported on its role in LUAD." (PMID 41323386, 2025).
multiple myeloma (3 papers, 2017 to 2025). "In multiple myeloma, low CD302 expression activates oncogenic MYC pathways, driving disease progression and poor prognosis, while high expression correlates with prolonged overall survival (OS)." (PMID 41323386, 2025). "In multiple myeloma (MM), the expression level of CD302 is closely correlated with patient survival." (PMID 41323386, 2025). "Thus, low CD302 expression may be closely associated with abnormal activation of the MYC pathway and the development of multiple myeloma." (PMID 41323386, 2025).
hepatocellular carcinoma (2 papers, 2022 to 2023). A malignant tumor that arises from hepatocytes. "In this study, we examined the relevance of ectopic and endogenously expressed CD302 during HCV infection of human hepatoma Huh-7.5 cells and explanted primary hepatocytes." (PMID 35297672, 2022). "Thus, ectopic expression of CD302 in a human hepatoma cell line limits HCV infection with a broad range of recombinant HCV chimeras expressing the structural proteins representing seven major HCV genotypes." (PMID 35297672, 2022).
type 2 diabetes (2 papers, 2015 to 2024). "The downregulation of cd302 can increase insulin secretion and promote β cell survival, which makes it an attractive target for developing new medicine to treat type II diabetes and its complications (such as diabetes nephropathy)." (PMID 39364045, 2024). "We selected 14 disallowed genes for analysis based on their identification in 2 independent studies (C1qbp, Cd302, Cxcl12, Igfbp4, Ldha, Lmo4, Maf, Oat, Pdgfra, Slc16a1, and Smad3) and/or other criteria including up-regulation in type 2 diabetes (Acot7, Ldha, and Pdgfra)." (PMID 26038943, 2015).
asthma (1 paper, 2020). "In current investigation, CD302 was strongly correlated with moderate-to-severe asthma." (PMID 32512817, 2020). "Several novel SNPs with large effect on asthma were identified in TNFRSF8/CD302 and BHMG1 genes." (PMID 32512817, 2020).
brain cancer (1 paper, 2022). A primary or metastatic malignant neoplasm affecting the brain. "Specifically, we identified four CpGs associated with CD302 and are predictive of survival in brain cancer, which are cg08347373, cg04735129, cg24859623, and cg20351640." (PMID 36401166, 2022).
Headache (1 paper, 2025). Cephalgia, or pain sensed in various parts of the head, not confined to the area of distribution of any nerve. "Genetically, CD302 was associated with headache (P = 2.60 × 10−5), RARRES2 was associated with neck or shoulder pain (P = 3.94 × 10−4), TNFRSF1B was associated with back pain (P = 7.96 × 10−5), and CD74 was associated with hip pain (P = 3.21 × 10−4)." (PMID 40048323, 2025).
Hepatitis (1 paper, 2025). Inflammation of the liver. "The images in columns I and III show liver sections with predominant immunostaining in zone 2 and 3 hepatocytes, thus emphasizing the intricate interaction between CD302 and DEC-205 in the context of diclofenac-induced hepatitis." (PMID 40565363, 2025).
large cell carcinoma (1 paper, 2025). A malignant epithelial neoplasm composed of large, atypical cells. "Considering that H460 is a large-cell carcinoma cell line and H1975 is primarily used for drug resistance studies, A549 and PC-9 cells were selected for the construction of the CD302-overexpressing cell model." (PMID 41323386, 2025).
leukemia (1 paper, 2025). A malignant (clonal) hematologic disorder, involving hematopoietic stem cells and characterized by the presence of primitive or atypical myeloid or lymphoid cells in the bone marrow and the blood. "CD302 serves as a delivery vehicle for pyrrolobenzodiazepines (PBDs) to eliminate HL-60 leukemia cells." (PMID 41323386, 2025).
lung adenocarcinoma (1 paper, 2025). A carcinoma that arises from the lung and is characterized by the presence of malignant glandular epithelial cells. "CD302 is expressed at low levels in lung adenocarcinoma tissues, and its expression is negatively correlated with tumor diameter, serving as an independent risk factor for poor prognosis in lung adenocarcinoma patients." (PMID 41323386, 2025). "Database analysis revealed that CD302 exhibited low expression in lung adenocarcinoma tissues, with its expression levels being negatively correlated with T stage, N stage, and TNM stage." (PMID 41323386, 2025). "Bioinformatics analysis of public databases revealed that CD302 expression was significantly downregulated in lung adenocarcinoma (LUAD) tissues, with its levels negatively correlated with T stage, N stage, and TNM stage." (PMID 41323386, 2025). "Moreover, using the human lung adenocarcinoma cell lines A549 and PC-9, a CD302 overexpression model was established." (PMID 41323386, 2025). "Analysis of clinical NSCLC samples validated the low expression of CD302 in lung adenocarcinoma, with expression levels showing a negative correlation with tumor diameter (correlation coefficient = -0.5358)." (PMID 41323386, 2025).
lung squamous cell carcinoma (1 paper, 2025). "In lung squamous cell carcinoma, CD302 overexpression associates with favorable outcomes, likely via suppression of tumor growth and metastasis through immunomodulation or angiogenesis regulation." (PMID 41323386, 2025). "In lung squamous cell carcinoma (LUSC), CD302 expression is significantly downregulated in tumor tissues and is positively correlated with angiogenesis, suggesting that it may influence LUSC progression by regulating tumor vascularization." (PMID 41323386, 2025).
membranous nephropathy (1 paper, 2026). "Proteomic-wide MR revealed MTR as protective in chronic GN and HCK as a risk factor for membranous nephropathy, whereas CD302 and CDKN1B showed protective effects." (PMID 41990104, 2026).
neuroendocrine tumors (1 paper, 2020). "In addition, CD302 had been identified as a biomarker to categorize the metastases of neuroendocrine tumors (NET), and it is reported to be overexpressed in high grade NET." (PMID 32775301, 2020).
prediabetes (1 paper, 2019). "With regard to PRRs, IL-33 was directly correlated with the C-type lectin receptor CD302 in individuals with normoglycemia (r = 0.54; P = 0.01; n = 21) and T2D (r = 0.41; P = 0.004; n = 47) but not in those with prediabetes." (PMID 31073344, 2019).
primary immunodeficiency (1 paper, 2020). "The GSEA analysis of LGG cases showed that those cases with high CD302 expression enriched gene sets involved in JAK/STAT signaling pathway, cytokine receptor interaction, and primary immunodeficiency." (PMID 32775301, 2020).
SAPHO syndrome (1 paper, 2019). SAPHO syndrome (acronym for Synovitis, Acne, Pustulosis, Hyperostosis and Osteitis) is an auto-inflammatory disease, mainly characterized by the association of neutrophilic cutaneous involvement and chronic osteomyelitis. "Other genes such as CD302, a C-type lectin receptor involved in cell adhesion and migration and CD151, known to complex with integrins and other transmembrane 4 superfamily proteins, were also up-regulated in SAPHO syndrome." (PMID 31395074, 2019).
infection (23 papers, 2004 to 2025). The state of being infected such as from the introduction of a foreign agent such as serum, vaccine, antigenic substance or organism. "Given empirical difficulties in isolating CypA-homozygous pups in the EFKI TRIM26H/H CD302-/- background, we utilized heterozygotes for subsequent infections." (PMID 40899815, 2025). "Lentiviral particle infection followed by puromycin selection was performed to establish stable CD302-overexpressing A549 and PC-9 cell lines." (PMID 41323386, 2025). "These include murine genes incompatible with HCV biology (CD81, OCLN, TRIM26, CypA) and those murine factors that actively inhibit infection (CD302, CR1L)." (PMID 40899815, 2025). "In general, these findings are in agreement with our previous report describing mouse Cd302 as an HCV restriction factor which limits infection of mouse hepatocytes." (PMID 35297672, 2022). "The transfected endoribonuclease-prepared small interfering RNAs (esiRNAs) modestly decreased CD302 cell surface expression at the time point of infection and slightly enhanced HCV infection compared to control-treated cells." (PMID 35297672, 2022). "Four days after infection, fewer focus-forming units were observed in HepG2/C3A (CD302) cells than HepG2/C3A (empty) cells (right), suggesting that CD302 reduced HEV infection in this cellular model." (PMID 35297672, 2022). "CD302 overexpression in Huh-7.5 cells potently inhibited infection of diverse HCV chimeras representing seven genotypes." (PMID 35297672, 2022). "Human CD302 restricts infection of chimeric HCV representing seven genotypes." (PMID 35297672, 2022). "Ectopic expression of CD302 and CD302 ΔCPT consistently downregulated HCVpp infection." (PMID 35297672, 2022). "Upon infection, we did not observe elevated HCV serum viremia above baseline in EFKI TRIM26H/H CD302-/- CypAH/H mice." (PMID 40899815, 2025). "Ectopic CD302 expression restricted infection of liver tropic hepatitis E virus (HEV), while it did not affect infection rates of two respiratory viruses, including respiratory syncytial virus (RSV) and the alpha coronavirus HVCoV-229E." (PMID 35297672, 2022).
tumor (7 papers, 2012 to 2025). "Collectively, this study elucidates the tumor-suppressive role of CD302 in LUAD, highlighting its potential as a novel diagnostic and therapeutic marker for this malignancy." (PMID 41323386, 2025). "ROC curve analysis was conducted to evaluate the diagnostic efficacy of CD302, revealing an area under the curve (AUC) of 0.912 (P < 0.001; 95% CI: 0.889–0.935), which underscores its high discriminative power in distinguishing tumor tissues from adjacent normal tissues." (PMID 41323386, 2025). "Leveraging TCGA data (59 normal and 539 tumor samples), bioinformatics analyses revealed significantly downregulated CD302 expression in LUAD tissues compared to normal counterparts." (PMID 41323386, 2025). "In summary, this study integrates bioinformatics, clinical sample analysis, and in vitro experiments to establish CD302 as a tumor suppressor in LUAD, where its downregulation correlates with poor prognosis and promotes malignant phenotypes." (PMID 41323386, 2025). "CD302 expression was significantly correlated with tumor diameter (P < 0.05), with expression gradually decreasing as tumor diameter increased." (PMID 41323386, 2025). "Results confirmed marked downregulation of CD302 in LUAD tumor tissues, which strongly correlated with patient prognosis." (PMID 41323386, 2025). "These six CD302/FABP5 correlated genes were reported to be involved in tumor cell proliferation, migration, invasion and EMT." (PMID 32775301, 2020). "Thus, CD302 expression level was unrelated to age, sex, T stage, N stage, M stage, TNM stage, and differentiation, but was associated with tumor diameter." (PMID 41323386, 2025). "In this study, public databases, bioinformatics analyses, and validation with clinical tissue samples were employed to demonstrate that CD302 is downregulated in LUAD tissues, with its expression negatively correlated with tumor diameter and exhibiting high diagnostic efficacy." (PMID 41323386, 2025). "Gene expression profiling of 598 LUAD samples (59 normal tissues and 539 tumor tissues) from The Cancer Genome Atlas (TCGA) database demonstrated that CD302 expression was significantly downregulated in both unpaired and paired LUAD tissues compared to normal controls (both P < 0.001)." (PMID 41323386, 2025). "The results showed downregulation of HOXD3, PRUNE2, CD302, CCDC8, and KLF2 (tumor vs. control)." (PMID 41186818, 2025). "Spearman correlation analysis further confirmed a negative correlation between tumor diameter and CD302 expression (r = -0.5358)." (PMID 41323386, 2025). "GSEA results showed LGG tumors with high expression of CD302 or FABP5 enriched JAK/STAT and ECM receptor interaction signaling pathway, which are reported to be involved in tumorigenesis and could promote tumor progression." (PMID 32775301, 2020). "Moreover, LGG tumors with CD302 or FABP5 overexpression highly expressed some oncogenes, including GPR65, PIK3CG, CHI3L1, and RAB36, which were reported to promote tumor growth and metastasis." (PMID 32775301, 2020).
cancer (5 papers, 2010 to 2025). A tumor composed of atypical neoplastic, often pleomorphic cells that invade other tissues. "Research on CD302 in oncology remains nascent, with heterogeneous expression and functional profiles observed across cancer types." (PMID 41323386, 2025).
cardiovascular diseases (1 paper, 2025). "Diet-associated proteins (e.g., FSTL3, STC1, and CD302 antigen) significantly mediate risk associations for various chronic disorders, including cardiovascular diseases and chronic respiratory diseases." (PMID 40823023, 2025).
CD302 also shares sentences with these, for which no sentence is quoted: viral infection (12 papers); bacterial infection (3); breast carcinoma (2); adenocarcinoma (1); brain tumors (1); cholesteatoma (1); cyst (1); diabetes nephropathy (1); essential hypertension (1); fungal infection (1); hepatitis C virus infection (1); Hodgkins lymphoma (1); Hypertension (1); neurodegenerative disease (1); Obesity (1); Parkinson (1).